APC (APC regulator of Wnt signaling pathway)
Diseases named in the same sentence as APC in open-access papers (continued):
Sharing a sentence is not in itself a finding about the gene and the disease.
colon carcinoma (continued). "These included a colon cancer cell line with a gain-of-function mutation in CTNNB1 (HCT116) and two colon cancer cell lines with APC loss-of-function mutations (DLD1 and SW480)." (PMID 26528816, 2015). "In colon cancer, it has been suggested that EGR1 serve as a tumor suppressor that is downregulated or lost as a consequence of APC mutation and the subsequent nuclear accumulation of β-catenin." (PMID 26343742, 2015). "The majority of colon cancers show a modification of the APC or β-catenin protein, which suggests an important role in the initiation of carcinogenesis of the colon." (PMID 25932044, 2015). "In colon cancer, APC expression was frequently downregulated, leading to the disassembly of β-catenin degradation complex." (PMID 26417932, 2015). "The c-myc gene has been identified as a direct target of LEF-1/TCF proteins, which are repressed by wild-type APC and activated by β-catenin in colon cancer cells." (PMID 26219398, 2015). "Our data in colon cancer showed that the majority of mutations identified were shared between a primary tumor and its cognate paired metastatic lesion, including KRAS, APC, and PIK3CA which are commonly tested mutations in our patients." (PMID 25974029, 2015). "The CID is a target of the selective pressure acting on APC during tumourigenesis, and it must be removed or inactiviated for the development of a colon carcinoma." (PMID 24416237, 2014). "The R414C mutation was first identified by Nishisho and colleagues in 1991 who were originally attempting to analyze four possible genes (MCC, TB2, SRP, and APC) which were involved in this inherited form of colon cancer in a cohort of ninety FAP patients." (PMID 24790607, 2014). "It was shown that allelic variation in the adenomatous polyposis coli (APC) gene expression plays a critical role in colon cancer." (PMID 25287681, 2014). "Our data demonstrate that GRP78 interacts with APC at its N-terminus in colon cancer cells whose COOH-terminal domains of APC are missing." (PMID 24977433, 2014). "The c-Myc transcription factor can be activated by the Wnt/APC pathway, which is deregulated in colon cancer." (PMID 25360631, 2014). "Inactivation of the tumor suppressor Adenomatous polyposis coli (APC) is observed at an early stage of colon tumor development." (PMID 23734346, 2013). "Colon cancer in women is by 60% less frequent than breast cancer (for example, APC methylation is also detected in cfDNA from colon cancer patients with considerable sensitivity)." (PMID 23320751, 2013). "Restoration of fully functional APC is sufficient to restore cell-cell adhesion and to reduce the tumorigenic properties of colon cancer cell lines." (PMID 24205248, 2013). "The APC+/min mouse model mimics the early events of colon cancer in humans and is widely used to test the effects of potential oncogenes and tumor suppressors on formation of intestinal tumors." (PMID 23799088, 2013). "The technique presented improves our understanding of cryptogenesis and suggests that excess colon crypt formation occurs when Wnt signaling is perturbed (e.g. by truncation of adenomatous polyposis coli, APC protein) in most colon cancers." (PMID 24205248, 2013). "APC normally down-regulates WNT signaling in human colon, and APC mutations cause proliferative abnormalities in premalignant crypts leading to colon cancer, but the mechanisms are unclear at the level of spatial and functional organization of the crypt." (PMID 24224156, 2013).
colon carcinoma (continued). "In the present work, we used RNA interference to down-regulate the level of APC in several colon cancer cell lines expressing truncated APCs of different lengths covering the MCR." (PMID 22509309, 2012). "Oncogenic mutation in β-catenin or other components of the destruction complex (APC or Axin) are observed in colon cancer, hepatocelluar carcinoma, and prostate cancer." (PMID 23071615, 2012). "Consistent with the ERK5 expression level, c-Myc and p68/p72 were expressed in colon tumors of Tg/APC at similar levels as W/APC, although the expression of p72 in some samples of Tg/APC was weak." (PMID 22876303, 2012). "To test this directly, we assessed both mutants in cultured human SW480 colon cancer cells, which carry a truncated version of human APC, and thus accumulate very high levels of ßcat in the cytoplasm and nucleus." (PMID 22359584, 2012). "MiR-143 was highly expressed in the small intestines tumors of Tg/APC whereas the colon tumors generally expressed lower." (PMID 22876303, 2012). "A tumor suppressive function for Ceacam1 has been suggested due to loss of expression in hyperplastic polyps, adenomas, as well as in human colon cancers that precedes defects in the APC pathway." (PMID 22496968, 2012). "These alterations in APC or alternatively, mutations in β-catenin result in deregulation of β-catenin turnover and increase β-catenin/TCF signalling in colon cancer." (PMID 23144924, 2012). "Transduction of colon cancer cell lines with miR-135a and miR-135b results in diminished APC expression and accumulation of β-catenin." (PMID 21403819, 2011). "It will be interesting to delineate how the plus-end tracking proteins function in colon cancer cells, with inactive APC and elevated MCAK, in context of the dynamics of MT cytoskeleton and cell motility." (PMID 22249213, 2011). "Cdc42 was also found to interact directly with both full-length APC and a truncation mutant APC1–1638, which is implicated in colon cancer." (PMID 21311754, 2011). "Most notably, all-trans-retinyl acetate sensitized premalignant adenoma cells of APC-deficient mice to TRAIL-induced apoptosis, thus establishing a paradigm for chemoprevention of colon cancer by retinoic acid-TRAIL combination therapy." (PMID 21463519, 2011). "To examine the effect of Cdc42V12 on APC localization in a more physiological context we decided to study these two proteins in two colon cancer cell lines." (PMID 21311754, 2011). "Nuclei of human APC-/- colon cancer cells contain stable β-catenin-TCF-4 complexes for target gene activation." (PMID 22022540, 2011). "In contrast, modules associated with mutations of APC and BRAF possess tissue-specific patterns, as APC and BRAF mutations occur primarily on colon cancer and melanoma samples respectively." (PMID 22051105, 2011). "Mutations in APC/adenomatous polyposis coli, CTNNB1/β-catenin or AXIN genes which activate Wnt/β-catenin pathway are responsible for the initiation of most colon cancers." (PMID 21858154, 2011). "For example, LINE-1 promoter hypomethylation is common in colon cancer, and the retrotransposal insertion of a LINE-1 sequence has been directly shown to disrupt the APC gene in a case of colon cancer." (PMID 20208994, 2010). "It is further interesting that colon cancer cells that expressed claudin-1 (HT29, SW480, and SW620) all harbor mutations in APC and have activated β-catenin/Tcf signaling." (PMID 20671913, 2010). "Similar dependence of claudin-1 expression in colon cancer cells upon APC and β-catenin signaling was also shown by others." (PMID 20671913, 2010). "One of the best-characterized tumor suppressor genes in colon cancer is the adenomatous polyposis coli (APC) gene." (PMID 20298593, 2010).
colon carcinoma (continued). "Our data suggest that localised phospho-β-catenin has distinct roles in normal epithelial cells and that the truncation of APC in many colon cancers would be expected to disturb these functions." (PMID 21152425, 2010). "APC siRNA and analysis of colon cancer cell lines show that functional APC is required for localised phospho-β-catenin accumulation in cell protrusions." (PMID 21152425, 2010). "The current paradigm for most colon cancers is that truncation of APC disrupts the regulation of the cellular concentration of β-catenin by proteasome-mediated degradation." (PMID 21152425, 2010). "Localised phospho-β-catenin/APC clusters accumulate in migrating cells and are lost in colon cancer cells when APC is truncated." (PMID 21152425, 2010). "Generally, colon cancers show either chromosomal instability (CIN), which correlates with loss of APC function, or microsatellite instability, which correlates with loss of mismatch repair function, but not both." (PMID 19822006, 2009). "Previously, APC has been detected in both the nucleus and cytoplasm of human colonic tissue, with more prevalent cytoplasmic staining in colonic tumors compared to normal tissue." (PMID 19845967, 2009). "Biallelic knockout of PPARγ in colonic epithelial cells resulted in increased tumor incidence and tumor size in APC+/Min mice, and Pioglitazone suppressed colon tumor growth in APC+/Min mice in a dose-dependent manner." (PMID 19884989, 2009). "Specifically, the HT-29 colon cancer cell line has a type II APC truncation mutation and the LS174T and HCT116 cell lines have a full length, wild type APC protein." (PMID 19460168, 2009). "In this study, HT-29 colon cancer cells with truncated APC have LEF-1/β-catenin complexes constitutively occupying a WRE in the cMYC enhancer." (PMID 19460168, 2009). "Themajor controversy in the PPARγ field has revolved around two high-profilepapers that reported increased colon tumor formation in APC+/Min mice treated with thiazolidinediones." (PMID 18615192, 2008). "PPARδ was elevatedin colon cancer cells and was repressed by APC gene via the β-catenin/Tcf-4response elements in its promoter." (PMID 18483618, 2008). "The companion paper reporteda slight, but significant, increase in the number of colon tumors in APC+/Min mice treated with troglitazone." (PMID 18615192, 2008). "One of these papersreported a significant increase in colon tumor size in APC+/Min micetreated with either troglitazone or rosiglitazone." (PMID 18615192, 2008). "Another Wnt component, APC, lead to elevated CLU levels when being over-expressed in a null APC-/- human colon cancer cell line." (PMID 17634137, 2007). "Deletion analysis indicated that the N-terminal region of the APC protein mediated its junctional localisation, consistent with our observation that truncated APC proteins in colon cancer cell lines are still capable of localising to the cell cortex." (PMID 16423286, 2006). "Consistent with this we find that colon cancer cell lines expressing truncated APC proteins are also capable of localising to the cortex in cells having the necessary cell-cell contacts." (PMID 16423286, 2006). "It has been reported that BMP-4 is overexpressed and secreted by human colon cancer cells with mutant APC genes." (PMID 15785755, 2005). "In an effort to isolate APC and its binding partners, the antibody APC(N15) was incubated with whole-cell lysate from SW480 colon carcinoma cells." (PMID 12610503, 2003). "Attenuated APC phenotype is characterized by relatively few colonic polyps, early age at onset of colon cancer compared with the general population, and inactivating germline mutations within specific regions of the APC gene." (PMID 11506490, 2001). "All the ipatasertib-resistant colon carcinoma lines were APC-mutant." (PMID 40761343, 2025).
colon carcinoma (continued). "Pioglitazone (agonist of PPARG) stimulates the growth of Adenomatous Polyposis Coli (APC)-mutated HT-29 human colon cancer cells, while troglitazone enhances colon cancer in normal C57BL/6 J mice." (PMID 40500799, 2025). "Considering that the HCT 116 cell line has a functional APC gene, we can conclude that this transcript could be a marker of APC deregulation in colon cancer." (PMID 40723829, 2025). "The authors explained that such accumulation of wild‐type β‐catenin can be explained by a mutation of the APC gene, such as in colon cancers, and this was not frequent in HCC because no predisposition to HCC was found in patients with polyposis." (PMID 40348604, 2025). "Moreover, the APC protein was less expressed in the colon tumor compared to the adjacent colonic mucosa." (PMID 39200196, 2024). "A docking study revealed that the potential mechanism by which 4g exerts its anti-colon cancer effect may be through inhabiting the binding of APC–Asef." (PMID 38998962, 2024). "Moreover, other signaling molecules such as APC in the Wnt/ β‐catenin signaling pathway have been shown to negatively affect YAP in colon cancer, while MST1/2 deletion in the Hippo/YAP pathway was shown to activate β‐catenin in hepatocellular carcinoma." (PMID 37558205, 2023). "In colon cancer cells with a normal Wnt pathway, Nox1 mediates Wnt-induced cell growth, but not in APC-deficient colon cancer cells, which have constitutive Wnt signaling activity." (PMID 37443096, 2023). "Given that more than 50% of CRC patients have APC mutations, the prognostic utility of RAI14 in APC-MUT colon cancer may provide early warning and increase the chance of successful treatment." (PMID 36934880, 2023). "To characterize the APC-dependent regulation of GSK-3 in more depth in vivo, we have examined the zebrafish apcmcr mutant, which has a truncating mutation in the mutation cluster region (mcr) that is similar to mutations associated with human colon cancers." (PMID 37489330, 2023). "Much experimental evidence has demonstrated that mutations in the Adenomatous Polyposis Coli (APC) gene, an essential negative modulator of β-catenin-dependent canonical Wnt signaling, trigger colon cancer progression." (PMID 37982965, 2023). "SND1 can promote colon cancer cells proliferation by suppressing APC and activating telomerase." (PMID 37885030, 2023). "A similar experiment was carried out in APC-WT colon cancer cell line RKO." (PMID 36934880, 2023). "As for the effect of GPCR signaling on WNT signaling, research has already shown that G-protein coupled lysophosphatidic acid receptors promote proliferation of colon cancer cells harboring wild-type APC via nuclear translocation of β-catenin through the PKC-GSK3β pathway." (PMID 37760541, 2023). "Survival analysis of RAI14 showed that high expression of RAI14 was significantly correlated with unfavorable prognosis of colon cancer patients in the APC-MUT tumors but less significant in the APC-WT tumors (log-rank test, p = 0.013 for APC-MUT tumors and p = 0.066 for APC-WT tumors)." (PMID 36934880, 2023). "Soon after, the APC gene product would be found to be an essential regulator of the intracellular Wnt cascade, leading to the establishment of constitutive Wnt activation as a key oncogenic driver in APC−/− colon carcinomas." (PMID 35663403, 2022).
colon carcinoma (continued). "Next, in comparison with the selected TNKSi panel, the potential of OM-153 as an antiproliferative agent was tested in a cell growth assay in the adenomatous polyposis coli (APC)-mutated, WNT/β-catenin signaling–dependent, and TNKSi-sensitive colon carcinoma cell line COLO 320DM." (PMID 36873622, 2022). "We gathered 42 cases of MSS/pMMR colon cancer tissues, including 22 APC-mt and 20 APC-wt." (PMID 35937946, 2022). "While we anticipated detecting genes previously implicated in colon cancer, the relative relationship to changes in CHRM1 expression suggests a common relationship between the concurrent changes observed in CHRM1 and APC/CTNNB1, and these downstream β-catenin target genes." (PMID 35370785, 2022). "Therefore, the A-f, T-f, and UB-010 fractions were capable of inhibiting HCT-116 colon cancer cell growth by targeting APC genes." (PMID 35631686, 2022). "In cases of both sporadic and hereditary CRC, two “hits” in APC trigger colon tumor formation." (PMID 35587635, 2022). "Therefore, APC-wt MSS/pMMR mainly includes TIMT I type colon cancer, which was consistent with the statistical result in the TCGA database." (PMID 35937946, 2022). "In colon cancer these mutations typically occur following APC mutation during tumorigenesis, though this order is not invariant." (PMID 35159051, 2022). "We divided 338 pMMR/MSS colon cancer from TCGA database into 261 APC-mt and 77 APC-wt." (PMID 35937946, 2022). "Together, APC and CTNNB1 account for the majority of WNT mutations in colon cancer." (PMID 35159051, 2022). "The results showed that many cancer-related pathways were enriched in high-risk groups such as cellular response to hypoxia, glycolysis and gluconeogenesis, metabolic reprogramming in colon cancer, APC mediated degradation of cell cycle proteins, signaling by EGFR." (PMID 36077637, 2022). "In colon cancer cells with partial APC gene knockout, PLK1 inhibits tumor growth." (PMID 36267311, 2022). "Furthermore, we further verified the relationship between APC genotype and TIMTs and the efficacy of immunotherapy in 42 colon cancer specimens." (PMID 35937946, 2022). "PPARβ/δ, which is highly expressed in colon cancer cells, was suppressed by the APC gene via the β-catenin/Tcf-4 response elements in its promoter region, although this mechanism is debatable, as disruption of APC in the mouse colon does not increase PPARβ/δ expression." (PMID 35163356, 2022). "For the cancer susceptibility genes identified in the cohort that are not involved in LS, we found several genes implicated in the hereditary colorectal cancer landscape: APC, MUTYH, POLE, POLD1, and BLM, as well as genes resulting in an increased risk of colon cancer as CHEK2." (PMID 36232851, 2022). "Further, a high number of R-spondin mutations and fusion proteins causing hyperactivation of Wnt signaling has been described in 10% of colon cancers lacking the APC mutations." (PMID 34552611, 2021). "The APC mutation is the first event triggering colon carcinogenesis both in the majority of sporadic cases and in familial adenomatous polyposis (FAP) syndrome, a hereditary form of colon cancer." (PMID 34679712, 2021). "Overexpression of either APC or APC2 in colon cancer cells that lack functional APC could inhibit Wnt signaling effectively." (PMID 34000297, 2021). "Moreover, our studies contributed to evidence its role in interacting with WNT/APC/β-catenin axis, highlighting new pathways in sporadic colon cancer onset." (PMID 33402733, 2021). "In addition, mice expressing the abnormal APC protein were shown to be more prone to colon tumor cell formation if the Nrf2 gene was ablated." (PMID 34443375, 2021).